RNASE4 (ribonuclease A family member 4)
Description:
Cleaves preferentially after uridine bases. Has antimicrobial activity against uropathogenic E.coli (UPEC). Probably contributes to urinary tract sterility.
Synonyms: RNS4; RAB1
Tractability: Small molecule: a structure with a bound ligand is known. Antibody: UniProt places it where antibodies can reach, with high confidence; its Gene Ontology location is reachable by antibodies, with high confidence; UniProt predicts a signal peptide or a membrane-spanning region. PROTAC: its protein half-life has been measured.
Gene: Protein-coding gene on chromosome 14 (20,682,598 to 20,701,216, forward strand). Ensembl gene ENSG00000258818.
Subcellular location: Secreted
Gene Ontology:
Molecular function: RNA nuclease activity; ribonuclease A activity; nucleic acid binding
Biological process: antibacterial humoral response; defense response to Gram-positive bacterium
Cellular component: extracellular region
Genetic constraint (gnomAD): Loss-of-function variants: 1 observed, 1.04 expected, observed/expected ratio (o/e) 0.96, 90% interval 0.26 to 1.89. That is too few expected variants to judge how well the gene tolerates losing a copy. Missense variants: 194 observed, 197.08 expected, observed/expected ratio (o/e) 0.98, 90% interval 0.88 to 1.11. Synonymous variants: 93 observed, 71.9 expected, observed/expected ratio (o/e) 1.29, 90% interval 1.09 to 1.54.
Homologues: Orthologues: chimpanzee RNASE4 (99% identical), macaque RNASE4 (96% identical), dog RNASE4 (84% identical), mouse Rnase4 (84% identical), rat Rnase4 (82% identical), pig RNASE4 (73% identical), zebrafish rnasel2 (29% identical), zebrafish rnasel3 (29% identical). Paralogues in human: RNASE1 (47% identical), ANG (36% identical), RNASE7 (36% identical), RNASE8 (35% identical), RNASE6 (33% identical), RNASE2 (29% identical), RNASE10 (27% identical), RNASE3 (27% identical), RNASE12 (23% identical), RNASE13 (23% identical), RNASE9 (22% identical), RNASE11 (21% identical).